NEK6 (NIMA related kinase 6)
Diseases named in the same sentence as NEK6 in open-access papers (continued):
Sharing a sentence is not in itself a finding about the gene and the disease.
thyroid cancer (4 papers, 2020 to 2021). "Fzd8 and NEK6 are overexpressed in thyroid cancer, where NEK6 is a circRNA that targets miR-370-3p, which targets Fzd8 3′UTR." (PMID 34671643, 2021). "circ-NEK6 functions as an oncogenic circRNA in thyroid cancer as it is significantly up-regulated and can promote the proliferation and invasion of cancer cells." (PMID 32140311, 2020). "Circ_NEK6 promotes thyroid cancer through sponging miR‐370‐3p and regulating Wnt." (PMID 33169939, 2020). "The results of mechanical trials have suggested that circ-NEK6 increases FZD8 mRNA expression, activates the wnt signaling pathway by interacting with miR-370-3p, which subsequently promotes the progression of thyroid cancer." (PMID 32140311, 2020).
cardiac hypertrophy (3 papers, 2014 to 2023). "Histological analyses of gross heart and H&E-stained LV tissue sections revealed an enhanced effect of Nek6 deficiency on pressure overload-induced cardiac hypertrophy." (PMID 24763737, 2014). "Therefore, we for the first time used Nek6-deficient mice to clarify whether the Nek6 is responsible for regulating cell cycle as well as cardiac hypertrophy." (PMID 24763737, 2014). "Knockout of NEK6 in mice led to the promotion of cardiac hypertrophy, dysfunction, and fibrosis through activation of AKT signaling, though no tumor studies were performed." (PMID 37046733, 2023). "We further examined Nek6 levels in the heart tissues of wild-type (WT) mice that underwent experimental cardiac hypertrophy models induced by TAC in different durations." (PMID 24763737, 2014). "Nek6−/− mice displayed augmented cardiac hypertrophy, dilatation, fibrosis and aggravated cardiac dysfunction, and the overexpression of Nek6 in H9c2 cells also confirmed the inhibitory effects of Nek6 on hypertrophy of cardiomyocytes." (PMID 24763737, 2014). "In conclusion, our results demonstrate that the cell cycle regulatory gene Nek6 is also a critical signaling molecule that helps prevent cardiac hypertrophy and inhibits the Akt signaling pathway." (PMID 24763737, 2014). "In summary, our present work provides in vivo and in vitro evidence that the expression of Nek6 prevents the cardiac hypertrophy, possibly due to block Akt signaling pathway activities that are unrelated to cell cycle progression." (PMID 24763737, 2014). "This suggests that a compensatory increase and subsequent de-compensatory decrease in Nek6 expression occurs during the progress of the cardiac hypertrophy." (PMID 24763737, 2014). "The loss- and gain-of-function experiments were performed in Nek6−/− mice and H9c2 cells transfected with the vector of pCMV-SPORT6-Nek6 to further elucidate the role of Nek6 in the development of cardiac hypertrophy." (PMID 24763737, 2014). "We deduced that the increased Nek6 might be a compensatory response of the heart to rivalry pressure overload-induced cardiac hypertrophy." (PMID 24763737, 2014). "Combining the results of previous reports with the current study, we speculate that the Akt signaling pathway at least partially contributes to the inhibitory effects of Nek6 on cardiac hypertrophy." (PMID 24763737, 2014). "Interestingly, our data demonstrated that Nek6 attenuated pressure overload-induced activation of the protein kinase B (Akt) pathway and cardiac hypertrophy." (PMID 24763737, 2014). "In the present study, the loss- and gain-of-function experiments were performed in Nek6 gene-deficient (Nek6−/−) mice and Nek6 overexpressing H9c2 cells to clarify whether Nek6 which promotes the cell cycle also mediates cardiac hypertrophy." (PMID 24763737, 2014). "Therefore, Nek6 could be another new effective therapeutic target against cardiac hypertrophy and heart failure." (PMID 24763737, 2014). "The absence of NEK6 promotes the progression of cardiac hypertrophy by activation of the Akt signaling pathway." (PMID 36266340, 2022). "We further demonstrated that the absence of Nek6 promoted cardiac hypertrophy, fibrosis, dilatation and cardiac dysfunction, which was accompanied by the significant activation of Akt/GSK-3β signaling in an experimental model of TAC." (PMID 24763737, 2014). "We got novel findings that the absence of Nek6 promoted cardiac hypertrophy, fibrosis and cardiac dysfunction, which were accompanied by a significant activation of the protein kinase B (Akt) signaling in an experimental model of TAC." (PMID 24763737, 2014). "However, the exact effect of Nek6 on cardiac hypertrophy has not yet been reported." (PMID 24763737, 2014).
clear cell renal cell carcinoma (3 papers, 2022 to 2025). "NEK6 is significantly upregulated in clear cell renal cell carcinoma (CCRCC) and significantly promotes CCRCC cell proliferation, migration, and invasion and inhibits apoptosis." (PMID 39895790, 2025). "These miRNAs directly target NEK6 mRNA and downregulate NEK6 expression, including miR-506-3p, miR-219-5p, and miR-141-3p, resulting in inhibition of cell proliferation and induction of apoptosis in retinoblastoma, HCC, and clear cell renal cell carcinoma." (PMID 35096064, 2022).
lung carcinoma (3 papers, 2008 to 2025). "LUSC AAF Sub-cohort: The activation of NIMA kinases (NEK9, NEK6, NEK7) pathway is closely linked to lung cancer cell cycle control, as these kinases regulate mitotic spindle formation and chromosomal stability, and their overexpression promotes proliferation, invasion, and poor prognosis in NSCLC." (PMID 41228248, 2025).
cervical cancer (2 papers, 2022 to 2026). A primary or metastatic malignant neoplasm involving the cervix. "Oncogenic kinases and methyltransferases including AURKA, AURKB, ESCO1, NEK6, and PRMTs that promote carcinogenesis are notably upregulated in cervical cancer." (PMID 41562705, 2026).
ciliopathies (2 papers, 2021 to 2022). "This bio-informatics approach unveils yet undescribed cilia and ciliopathy genes associated with COPD including NEK6 and PROM2 that may contribute to the pathology, and suggests a COPD endotype exhibiting ciliopathy features (CiliOPD)." (PMID 33639936, 2021).
colon adenocarcinoma (2 papers, 2022). "The activity of NEK6 is enhanced in several cancer cells, including colon adenocarcinoma (COAD) cells." (PMID 35096064, 2022). "However, the role and regulatory mechanism of NEK6 on the development of colon adenocarcinoma (COAD) are not fully understood." (PMID 35096064, 2022).
endometrial cancer (2 papers, 2023 to 2025). Primary or metastatic malignant neoplasm involving the endometrium (mucous membrane that lines the endometrial cavity). "Our study found that NEK6 was upregulated in human EC tissues, especially in endometrioid adenocarcinoma, the most common type of endometrial carcinoma (data not shown)." (PMID 41560755, 2025). "However, there have been no reports on the involvement of PRMT2, NEK6, NACC1, ATP2A2, and TM4SF19 in endometrial cancer." (PMID 37780629, 2023).
glioblastoma (2 papers, 2022 to 2023). The most malignant astrocytic tumor (WHO grade IV). "Similar observations were observed for glioblastoma cells, with depletion of either NEK6 or NEK7 leading to increased tubulation." (PMID 37099601, 2023). "As a further test, we performed NEK6/7 siRNA knockdown in glioblastoma cells and observed an increase in the size of EEA1-marked vesicles after depletion of NEK7 but not NEK6, suggesting cell type–specific requirements for NEK functions." (PMID 37099601, 2023).
head and neck squamous cell carcinoma (2 papers, 2022 to 2025). A squamous cell carcinoma that arises from any of the following anatomic sites: lip and oral cavity, nasal cavity, paranasal sinuses, pharynx, larynx, and salivary glands. "In head and neck squamous cell carcinoma (HNSCC), NEK6 is significantly upregulated, indicating poor prognosis in HNSCC patients." (PMID 39895790, 2025).
kidney cancer (2 papers, 2022). Primary or metastatic malignant neoplasm involving the kidney. "We have demonstrated that FAM13A-AS1 exerts its carcinogenic function by forming the lncRNA/miRNA/target axis with miR-141-3p and NEK6 in kidney cancer cell lines." (PMID 35402517, 2022). "In kidney cancer, studies revealed that miR-141-3p regulated NEK6 to influence cell proliferation, migration, and apoptosis of tumor cells." (PMID 36189312, 2022).
osteosarcoma (2 papers, 2011 to 2025). A usually aggressive malignant bone-forming mesenchymal neoplasm, predominantly affecting adolescents and young adults. "For example, in osteosarcoma, NEK6 accelerates tumor progression through STAT3-mediated signaling, contributing to poor prognosis." (PMID 41154634, 2025). "CDK 9 overexpression also increased proliferation of human osteosarcoma cell line U20S2, while CRK, CDK9, DCAF7, NEK6, GNB1, SPOP, and WW2 also increased proliferation in mouse fibroblasts." (PMID 21629697, 2011).
pancreatic ductal adenocarcinoma (2 papers, 2022 to 2023). An infiltrating adenocarcinoma that arises from the epithelial cells of the pancreas. "Furthermore, both NEK6 and NEK7 have negative correlations for patient survival outcomes in liver hepatocellular carcinoma and pancreatic ductal carcinoma." (PMID 37046733, 2023).
retinoblastoma (2 papers, 2020 to 2022). A malignant tumor that originates in the nuclear layer of the retina. "A recent study showed that MiR-506-3p directly targets NEK6 mRNA, decreasing its expression and leading to reduced cell proliferation, G0/G1 cell cycle arrest, and apoptosis in retinoblastoma cells." (PMID 32294979, 2020). "A recent study showed that NEK6 is regulated by long non-coding RNA homeobox A11 antisense RNA (HOXA11-AS) through MiR-506-3p in retinoblastoma." (PMID 32294979, 2020). "Thus, MiR-506-3p acts as a tumor suppressor through the regulation of NEK6 expression in retinoblastoma cells." (PMID 32294979, 2020). "In addition, NEK6 and HOXA11-AS are overexpressed in retinoblastoma tissues, while the tumor suppressor Mir-506-3p is downregulated; these findings agree with previous findings." (PMID 32294979, 2020).
asthma (1 paper, 2026). "In ex vivo severe asthma bronchial biopsies, the protein levels were upregulated 1.2-fold for PHLDB2 (p = 0.2844), 2.4-fold (p < 0.01) for NEK6, and 2.0-fold for SCNN1G (p < 0.05)." (PMID 41664127, 2026).
B-cell lymphoma (1 paper, 2023). "NEK6 is involved in mitosis and, if overexpressed, may result in human B-cell lymphoma." (PMID 37197974, 2023).
bladder carcinoma (1 paper, 2023). "Additionally, NEK6 and NEK9 both have negative correlations for patient survival outcomes in bladder carcinoma and positive correlations for patient survival outcomes in uterine corpus endometrial carcinoma." (PMID 37046733, 2023).
Bladder Urothelial Carcinoma (1 paper, 2022). "However, NEK6 expression are decreased in Bladder Urothelial Carcinoma (BLCA), renal chromophobe cells (KICH), and Lung squamous cell carcinoma(LUSC)." (PMID 35898455, 2022).
Cerebral ischemia (1 paper, 2024). Restriction of arterial blood supply to the brain associated with insufficient oxygenation to support the metabolic requirements of the tissue. "The aim of this study was to investigate the molecular mechanism of Nek6 alleviating CIRI through autophagy after cerebral ischemia." (PMID 39702325, 2024). "Through bioinformatics analysis of data set GSE93376 in Gene Expression Omnibus (GEO) database and comparison of gene differential expression in cerebral ischemia region of MCAO and control group, we found the candidate differential gene never in mitosis gene A (NIMA)-related kinase 6 (Nek6)." (PMID 39702325, 2024).
colon cancer (1 paper, 2022). "In this paper, we confirmed that miR-323a-3p could also negatively regulate NEK6 expression in COAD cells through binding with complementary 3′-UTR sequences in target NEK6 mRNA by luciferase reporter assay and binding site mutation analysis and block the proliferation of colon cancer cells." (PMID 35096064, 2022). "Our results indicate that miR-323a-3p targets NEK6 mRNA to functionally alter downstream NEK6 expression and arrest subsequently colon cancer cell proliferation." (PMID 35096064, 2022).
esophageal adenocarcinoma (1 paper, 2022). A malignant tumor with glandular differentiation arising predominantly from Barrett mucosa in the lower third of the esophagus. "The expression level of NEK6 in esophagitis tissue is similar to that in esophageal adenocarcinoma, and overexpression of the NEK6 gene increases in proportion to the severity of esophagitis." (PMID 35096064, 2022).
esophagitis (1 paper, 2022). An acute or chronic inflammatory disease affecting the esophageal wall. "In addition, NEK6 has also been associated with inflammation-based diseases, such as esophagitis and ulcerative colitis." (PMID 35096064, 2022).
ischemic stroke (1 paper, 2024). A stroke disorder caused by obstruction of blood flow to the brain, due to thrombotic (local blood clot formation) or embolic (due to a blood clot or other material traveling from another site) event. "This study confirmed that Nek6 regulates autophagy and alleviates CIRI through the mTOR signaling pathway, which provides a novel therapeutic strategy for patients with ischemic stroke in the future." (PMID 39702325, 2024).
myasthenia gravis (1 paper, 2025). Myasthenia gravis (MG) is a rare, clinically heterogeneous, autoimmune disorder of the neuromuscular junction characterized by fatigable weakness of voluntary muscles. "Moreover, NEK6 expression was also found to be downregulated in patients with myasthenia gravis, suggesting that decreased NEK6 expression may impair muscle cell regeneration and contribute to the development of sarcopenia." (PMID 40977679, 2025).
Obesity (1 paper, 2022). Accumulation of substantial excess body fat. "Seven of the genes were downregulated by obesity and reversed by VSG specific weight loss including Ido1, Aldoc, Tmem125, Dgki, Slc7a4, Msc, and Ephb3, while four were inversely regulated with obesity elevating Klhl5, Nek6, Arhgap20, and Hp." (PMID 35775614, 2022).
prostate adenocarcinoma (1 paper, 2023). "The GEPIA platform was used to measure the correlation between the antioxidant protein expression: Superoxide Dismutase 1 and 2 (SOD1 and SOD2) and peroxiredoxin 3 (PRDX3) with the NEK6 gene expression in prostate adenocarcinoma samples." (PMID 36672191, 2023).
sarcopenia (1 paper, 2025). Progressive decline in muscle mass due to aging which results in decreased functional capacity of muscles. "This study identified NOX4 and NEK6 as dual diagnostic biomarkers for SSc-associated sarcopenia through integrative bioinformatics and machine learning approaches." (PMID 40977679, 2025). "PCR validation confirmed the differential expression of NOX4 and NEK6 in both SSc and SSc-associated sarcopenia, demonstrating high predictive accuracy." (PMID 40977679, 2025). "NOX4 (AUC = 0.798, 95% CI: 0.633 – 0.962) and NEK6 (AUC = 0.873, 95% CI: 0.749 – 0.996) exhibited high diagnostic accuracy for SSc-associated sarcopenia." (PMID 40977679, 2025). "This study proposes NOX4 and NEK6 as novel biomarkers, offering a non-invasive strategy for the early detection of SSc-associated sarcopenia." (PMID 40977679, 2025). "Our results establish NOX4 and NEK6 as novel diagnostic biomarkers for SSc-associated sarcopenia and propose a non-invasive strategy for its early detection." (PMID 40977679, 2025). "In order to more precisely evaluate the variations in their expression levels and determine whether there is statistical significance, we therefore intend to increase the sample size in subsequent research on NOX4 and NEK6 in SSc associated sarcopenia." (PMID 40977679, 2025). "This pattern may indicate that NOX4 and NEK6 may have an potential association between SSc and sarcopenia." (PMID 40977679, 2025). "The model positions NOX4 and NEK6 as pivotal contributors to SSc-associated sarcopenia." (PMID 40977679, 2025). "In the sarcopenia dataset GSE167186, NOX4 expression was elevated, and NEK6 expression was reduced in sarcopenia patients compared with controls." (PMID 40977679, 2025). "In contrast, both sarcopenia-related datasets and our independent qPCR validation cohort demonstrated markedly reduced NEK6 expression in peripheral blood samples of SSc patients relative to healthy individuals." (PMID 40977679, 2025). "For sarcopenia, the risk score was: normalized expression of NOX4 × 2.229 + normalized expression of NEK6 × (–2.369)." (PMID 40977679, 2025). "Five key CGs—NOX4, STC2, NEK6, IGSF10, and EMX2—were identified as molecular links between SSc and sarcopenia." (PMID 40977679, 2025). "In the sarcopenia dataset, the AUC for NOX4 was 0.662 (95% CI: 0.524 – 0.801), and for NEK6, it was 0.661 (95% CI: 0.533 – 0.789), suggesting limited individual predictive efficacy in sarcopenia." (PMID 40977679, 2025). "In the sarcopenia dataset (GSE167186), the individual AUC values for NOX4 and NEK6 were 0.662 (95% CI: 0.524 – 0.801) and 0.661 (95% CI: 0.533 – 0.789) respectively." (PMID 40977679, 2025).
splenic marginal zone lymphoma (1 paper, 2024). Splenic marginal zone lymphoma is a rare, indolent B-cell non-Hodgkin lymphoma characterized by abnormal clonal proliferation of mature B-lymphocytes with involvement in the spleen, bone marrow and, frequently, the blood. "MicroRNA-26b is significantly downregulated (P = 0.0016) in HCV+ splenic marginal zone lymphoma (SMZL) and this might cause miR-26b to stop inhibiting never in mitosis gene A (NIMA)-related Kinase 6 (NEK6) and have oncogenic potential in HCV-associated SMZL." (PMID 38482011, 2024).
systemic sclerosis (1 paper, 2025). A chronic disorder, possibly autoimmune, marked by excessive production of collagen which results in hardening and thickening of body tissues. "Notably, analysis of the SSc dataset (GSE181549) revealed significantly elevated NEK6 expression in lesional skin biopsies of patients with systemic sclerosis compared to healthy controls." (PMID 40977679, 2025).
ulcerative colitis (1 paper, 2020). An inflammatory bowel disease involving the mucosal surface of the large intestine and rectum. "In addition, inflammation-based diseases, such as ulcerative colitis, have also been linked to NEK6." (PMID 32294979, 2020). "NEK6 was found to be overexpressed in patients with more extensive colon involvement and long-term ulcerative colitis." (PMID 32294979, 2020). "Thus, NEK6 could be an early marker of CRC in patients with ulcerative colitis." (PMID 32294979, 2020).